SLC35F6 (solute carrier family 35 member F6)
Description:
Involved in the maintenance of mitochondrial membrane potential in pancreatic ductal adenocarcinoma (PDAC) cells. Promotes pancreatic ductal adenocarcinoma (PDAC) cell growth. May play a role as a nucleotide-sugar transporter.
Synonyms: ANT2BP; C2orf18; FLJ20555; TANGO9
Tractability: Antibody: UniProt predicts a signal peptide or a membrane-spanning region. PROTAC: ubiquitination databases record sites on it; its protein half-life has been measured.
Gene: Protein-coding gene on chromosome 2 (26,764,240 to 26,781,231, forward strand). Ensembl gene ENSG00000213699.
Subcellular location: Mitochondrion; Lysosome membrane
Subcellular location (Human Protein Atlas): Vesicles; Cytosol; Nucleoplasm
Gene Ontology:
Molecular function: protein binding; transmembrane transporter activity
Biological process: negative regulation of mitochondrial outer membrane permeabilization involved in apoptotic signaling pathway; positive regulation of cell population proliferation; transmembrane transport
Cellular component: extracellular exosome; lysosomal membrane; mitochondrion; membrane; lysosome
Genetic constraint (gnomAD): Loss-of-function variants: 26 observed, 28.6 expected, observed/expected ratio (o/e) 0.91, 90% interval 0.67 to 1.26. The upper end of that interval is the gene's LOEUF score, 1.26, which puts it in group 5 of 6, group 1 being the genes least tolerant of losing a copy. Missense variants: 428 observed, 491.31 expected, observed/expected ratio (o/e) 0.87, 90% interval 0.8 to 0.94. Synonymous variants: 174 observed, 205.13 expected, observed/expected ratio (o/e) 0.85, 90% interval 0.75 to 0.96.
Homologues: Orthologues: chimpanzee SLC35F6 (99% identical), macaque SLC35F6 (95% identical), pig SLC35F6 (94% identical), dog SLC35F6 (94% identical), rabbit SLC35F6 (93% identical), guinea pig SLC35F6 (91% identical), mouse Slc35f6 (87% identical), rat Slc35f6 (82% identical), tropical clawed frog slc35f6 (76% identical), zebrafish slc35f6 (73% identical), Caenorhabditis elegans C29H12.2 (50% identical), Drosophila melanogaster Tango9 (34% identical).
Diseases named in the same sentence as SLC35F6 in open-access papers:
SLC35F6 is named in the same sentence as 2 diseases in open-access papers, as found by Europe PMC text mining. Sharing a sentence is not in itself a finding about the gene and the disease. The quoted sentences say what the papers report.
Headache (1 paper, 2018). Cephalgia, or pain sensed in various parts of the head, not confined to the area of distribution of any nerve. "We identified numerous genes associated with headache, both temporal and other types: POFUT2 in CD4 cells, and SLC35F6, HTD2, ZNF708, KLRC4-KLRK1 and JMJD7 in CD8 cells." (PMID 30037347, 2018).
SLC35F6 also shares sentences with these, for which no sentence is quoted: endometrial cancer (1 paper).